PRMT5 (protein arginine methyltransferase 5)
Diseases named in the same sentence as PRMT5 in open-access papers (continued):
Sharing a sentence is not in itself a finding about the gene and the disease.
tumor (continued). "We suggest that the phosphorylation of PRMT5 is critical for enzymatic activity and tumour development." (PMID 38474089, 2024). "In our data, it is confirmed that the subcutaneous tumor established by Hs683 has less expression of MTAP and hardly affects the expression of PRMT5 compared with the mixed subcutaneous tumor inoculated with Hs683 and HMC3." (PMID 39711357, 2024). "“Combined inhibition of MTAP and MAT2a mimics synthetic lethality in tumor models via PRMT5 inhibition” JBC submission, September 2023." (PMID 38000655, 2024). "PRMT5 regulates a number of proliferative and biosynthetic processes and has been demonstrated to be important for proliferation in tumor models in vivo." (PMID 39711357, 2024). "PRMT5 is a widely expressed arginine methyltransferase that regulates processes involved in tumor cell proliferation and survival." (PMID 39068290, 2024). "To verify that circGSK3β promotes immune evasion and tumor progression via miR-338-3p/PRMT5, we first assessed its impact on immune evasion in BC cells." (PMID 39366935, 2024). "PRMT5 is a histone methyltransferase that suppresses transcription of several tumor suppressors and cell cycle inhibitors and promotes Wnt/β-catenin signaling and invasion." (PMID 39478125, 2024). "The PRMT5/MTHFD1 axis promotes tumor resistance and accelerates its metastasis in oesophageal squamous cell carcinoma." (PMID 38226966, 2024). "Our results have provided a rational combination therapeutic strategy targeting multiple PRMT5-coordinated tumor-promoting processes for the treatment of R/R MCL with high mutation burdens." (PMID 36797243, 2023). "The results, therefore, highlight the interplay between the E2F pathway and PRMT5, with antigen presentation by tumour cells to the immune system." (PMID 36841868, 2023). "In contrast, RhoA activating kinase (ROK) phosphorylates PRMT5 at T80 enhancing its activity on H4R3me2s and activating proto-oncogenes, contributing to tumor formation in hepatocellular carcinoma." (PMID 37928266, 2023). "Seeking a molecular mechanism that explains the tumor-specific high correlation between PRMT5 and APE1 expression, we consider it significant that the genomic locations of PRMT5 and APE1 are very close to each other at chr 14q11.2." (PMID 37887269, 2023). "The authors also demonstrated the correlation between PRMT5 and the anti-tumor immune response by in vivo experiments." (PMID 36980950, 2023). "Protein arginine methyltransferase 5 (PRMT5) has emerged as an important epigenetic regulator with essential roles in promoting tumor growth and survival." (PMID 37861290, 2023). "A recent study also corroborates our finding by showing that PRMT5 exhibits anti-tumor effects via regulation of necroptosis." (PMID 36658119, 2023). "Lastly, we report the development of a small molecule inhibitor (PRT382) with enhanced PRMT5 selectivity, improved tolerability, and optimal in vitro and in vivo anti-tumor activity compared to currently available PRMT5 inhibitors." (PMID 36609611, 2023). "PRMT5 protein expression levels were significantly elevated (4.4 fold) in tumor samples compared with normal samples." (PMID 37400960, 2023). "To validate the antitumor effect of PRMT5 inhibitors in vivo, we also injected PRMT5-knockout Granta-519 into mice and the result confirmed that PRMT5 knockout robustly inhibited the tumor growth." (PMID 36797243, 2023). "Both MTA uptake or PRMT5 inhibitor resulted in decreased cell viability in MTAP-deleted tumor cells compared with MTAP-expressing tumor cells." (PMID 37091983, 2023). "To evaluate the in vivo anti-tumor effect of PRT382 we first confirmed that the Eμ-PRMT5/TCL1 bulk tumor population was amenable to adoptive transfer into immunocompetent C57BL/6J syngeneic mice." (PMID 36609611, 2023).
tumor (continued). "It will be worth investigating how TRAF6 and PRMT5 coordinatively control these signaling pathways to regulate various biological processes, cell proliferation, migration, and tumor growth." (PMID 37173967, 2023). "Pharmacological inhibition of PRMT5 or adjusting E2F1 levels qualitatively altered the repertoire of lncRNA-derived peptide antigens displayed by tumour cells." (PMID 36841868, 2023). "Compared to G3BP2-R468K mutation, G3BP2-WT dramatically rescued the inhibitory effect of PRMT5 silencing on tumor growth." (PMID 36878903, 2023). "Using ibrutinib-resistant MCL-PDX model, treatment with PRMT5 inhibitor PRT382 significantly reduced tumor burden and improved median survival in mouse models." (PMID 37626420, 2023). "It has been reported that PRMT5 overexpression promoted tumor growth, while depletion of PRMT5 inhibited tumor growth." (PMID 37400960, 2023). "PRMT5 has been previously shown to be overexpressed in approximately 75% of CRC patient tumor samples and negatively correlated with CRC patient survival." (PMID 38203325, 2023). "GSK3368715 is a reversible type I PRMTs inhibitor that synergistically inhibits tumor growth when combined with PRMT5 inhibitors." (PMID 37699892, 2023). "Knockdown or pharmaceutical inhibition of PRMT5 is sufficient to decrease glycolysis flux, attenuate tumor growth, and enhance the antitumor effect of Taxol." (PMID 36999124, 2023). "The genetic ablation of PRMT5 resulted in remarkably reduced cell proliferation of Granta-519, consistent with the tumor proliferation suppressive effect of PRMT5 inhibitors." (PMID 36797243, 2023). "Although PRMT5 is mainly localized in the cytoplasm of tumor cells, our analyses show that tamoxifen triggers its nuclear translocation in tamoxifen‐sensitive tumors but not in resistant ones." (PMID 37458145, 2023). "In this report, we combine a clinically approved PARP inhibitor with a potent, selective inhibitor of PRMT5 to demonstrate increased anti-tumor activity in vitro and in vivo." (PMID 37596538, 2023). "Xenografted tumor analysis revealed that PRMT5 inhibitor treatment can attenuate tumor growth and metastasis." (PMID 36980950, 2023). "CLL LN tumors were intermittently populated with small CD3+ T cells with distinct cytologic morphology from small-to-medium-sized tumor blasts with PRMT5 positivity." (PMID 36609611, 2023). "Other studies have demonstrated that PRMT5 inhibition effectively suppressed tumor growth in both differentiated GB cells and GSCs and prolonged the survival of patient-derived xenograft models." (PMID 37298093, 2023). "GSK3326595 is a selective substrate-competitive PRMT5 inhibitor with potential antitumor and antiproliferative activity, which has shown efficacy in various tumor models." (PMID 38136401, 2023). "Inhibiting MAT2A and reducing SAM levels has been proposed to cause PRMT5 inhibition both by removing its substrate and, in the case of MTAP-negative tumours, by providing a greater opportunity for MTA binding." (PMID 37795443, 2023). "Distinct from CARM1, PRMT5 inhibition suppressed the induction of tumor antigen-specific CD8+ T cells in vitro." (PMID 35493527, 2022). "It is noteworthy that the evidence in support of the tumor-promoting function of PRMT5 were mainly inferred from in vitro studies 13-19." (PMID 35864961, 2022). "Genetic silencing of PRMT5 robustly inhibited CCSST tumor cell growth and EWSR1-ATF1-driven gene transcription." (PMID 36041632, 2022).
tumor (continued). "We found that PRMT5 was aberrantly overexpressed in tumor samples, resulting in poor overall survival in our cohort and that it was correlated with the progress of the disease, as shown in the stained BC tissue." (PMID 36199122, 2022). "To place this finding into context, we analyzed the correlation of MYC and PRMT5 mRNA expression across tumor entities." (PMID 35439169, 2022). "Taken together, this paper indicates that CUL4A promotes the proliferation, migration, invasion of NPC cells, and tumor growth by promoting PRMT5 to activate NF-κB signaling." (PMID 35333690, 2022). "The phosphorylation and dephosphorylation of tyrosine and threonine residues of PRMT5 have an effect on its enzyme activity, and therefore, on the pathomechanism of tumour formation." (PMID 36232624, 2022). "In the xenograft tumor model, CAMK2N1 knockdown remarkably abolished the PRMT5 loss-induced growth inhibition of PC-3 xenografts." (PMID 35624451, 2022). "Consistently, in a PRMT5-knockdown tumor model, a higher abundance of NKs, DCs, and MDSCs were observed when compared with the control-knockdown model." (PMID 35493527, 2022). "We illustrate that PRMT5 inhibition not only attenuates primary tumor growth, but also potently blocks metastasis in both orthotopic implantation and metastatic models." (PMID 35803962, 2022). "By controlling transcriptional regulation, the epigenetic landscape, mRNA processing and splicing, or oncogenic signaling pathways, PRMT5 plays a crucial role in tumor maintenance." (PMID 35439169, 2022). "This tumor type appears particularly vulnerable to splicing dysregulation elicited by PRMT5 inhibition or knockdown." (PMID 35406598, 2022). "Together, this paper indicated that CUL4A promoted the proliferative, invasive, and migratory aptitude of NPC cells as well as tumor growth by promoting PRMT5 to activate NF-κB signaling." (PMID 35333690, 2022). "PRMT5 protein was preferentially located in the nuclei of tumor cells, with a small proportion in the cytoplasm shown by diffused or non-granular staining pattern." (PMID 35624451, 2022). "Together, these results indicated that CUL4A promoted the proliferative, invasive, and migratory aptitude of NPC cells as well as tumor growth by promoting PRMT5 to activate NF-κB signaling." (PMID 35333690, 2022). "PRMT5 inhibition significantly reduced tumor volume in an MCL and a DLBCL patient-derived xenograft and Z-138 xenograft models without inducing toxicity, as shown by the maintenance of the animal’s weight." (PMID 36167829, 2022). "In tumour cells, the inhibitory phosphorylation of MP is increased, leading to higher phosphorylation levels of PRMT5 at T80 by ROK." (PMID 36232624, 2022). "The results showed a dramatic decrease in the number of tumor nodules visible on the surface of the liver from liver-specific Prmt5 KO mice." (PMID 36499164, 2022). "We found that PRMT5 knockdown inhibited cell migration and invasion and slowed tumor growth in nude mice." (PMID 35333690, 2022). "Since knocking down PRMT5 in tumor cells can not only inhibit tumor cell proliferation but can also increase cell apoptosis, we further analyzed the effects of compounds A, B, and C on MDA-MB-231 cell apoptosis." (PMID 35563196, 2022). "Treatment with GSK3326595 (PRMT5 inhibitor) plus anti-PD-1 antibody enhanced the anti-tumor response in the mouse organism." (PMID 36713412, 2022). "In the TME of a PRMT5 knockdown transplanted tumor model, PD-1 and TIM-3 expression and function were both inhibited in CD8+ T cells." (PMID 35493527, 2022). "Among the different PRMT5 inhibitors evaluated, CMP5 blocks the PRMT5 activity, inducing apoptosis of differentiated cells and senescence in immature primary tumor cells." (PMID 35406768, 2022). "In particular, these genes are associated with more aggressive tumor phenotype (SAL2), migration and invasion (TOX4, PRMT5, AJUBA) development and progression (ZNF219, CEBPE)." (PMID 34944989, 2021).
tumor (continued). "In Eμ-myc transgenic mice, MYC directly upregulates PRMT5 and tumor progression is delayed after heterozygous deletion of the PRMT5 gene." (PMID 33989303, 2021). "In PRMT5 knockdown tumor microenvironment, we found the expression of PD-1 on the surface of T cells was decreased and the function of T cells was restored." (PMID 34522232, 2021). "Inhibiting PRMT5 affected anti-tumor immunity by limiting the infiltration of Treg cells into tumor sites." (PMID 34675933, 2021). "Similar to PRMT2, PRMT5 activity in GBM cells has been linked to cell stemness and tumour cell ability to self-renew." (PMID 33404912, 2021). "The sub-cellular localization of PRMT5 plays a major role in tumor progression; therefore, we investigated its location in untreated cells and in ones exposed to different treatments." (PMID 34200178, 2021). "PRMT5 epigenetically suppresses the expression of several tumor suppressor miRNAs, such as miR33b, miR96, and miR503, which bind to and target the mRNA corresponding to Cyclin D1 and/or c-Myc." (PMID 34006904, 2021). "We found that in PRMT5 knockdown tumor microenvironment, the expression of IFN-γ and TNF-α in CD4+ T and CD8+ T cells were increased, and the expression of granzyme B in CD8+ T cells was also upregulated." (PMID 34522232, 2021). "Rationale: Protein arginine methyltransferase 5 (PRMT5) is an oncogene that promotes tumor cell proliferation, invasion and metastasis." (PMID 34522232, 2021). "Most studies that exploited the anti-tumor potential of AMI-1 by targeting PRMT5 used a high dose of AMI-1 (in the mM range)." (PMID 34200178, 2021). "Studies also found that EBV utilizes PRMT5 to target and silence genes with important tumor suppressor properties during B-cell immortalization." (PMID 34513846, 2021). "We further used data obtained from TCGA cohort to analyze the expression levels of PRMT5 in normal cervical tissues and tumor tissues." (PMID 34522232, 2021). "Pharmacological inhibition and genetic deletion of PRMT5 in human hematopoietic and solid tumor cell lines has been reported to lead to growth arrest and tumor cell death." (PMID 33989303, 2021). "In comparison to tumors derived from parental LLC cells, those with stable PRMT5 depletion using mouse‐specific shRNAs exhibited significantly reduced tumor growth and weight, demonstrating that knockdown of PRMT5 attenuated tumor development." (PMID 34026434, 2021). "Long intergenic non-coding RNA 1q21.2 (LINC01138) has been shown to correlate with PRMT5 expression as well as HCC tumor size, AFP levels, and hepatitis B surface antigen levels." (PMID 33768972, 2021). "Compared to control group, the percentage and the number of CD4+ T and CD8+ T cells in PRMT5 knockdown tumor microenvironment were significantly higher." (PMID 34522232, 2021). "PRT543 demonstrates a high degree of selectivity for PRMT5 and potent anti-tumor activity and is currently being tested in a phase I human clinical trial for the treatment of advanced solid tumors and hematological malignancies (NCT03886831)." (PMID 33989303, 2021). "In subcutaneously implanted groups, knockdown of PRMT5 resulted in a significant reduction in tumor growth, whereas overexpression of PRMT5 showed the opposite result." (PMID 33953349, 2021). "The transcriptional-repressive function of PRMT5 is also crucial for epithelial-mesenchymal transition (EMT), a hallmark of tumor progression." (PMID 33953349, 2021). "The immunomodulatory effect of PRMT5 inhibitors on the tumour microenvironment will also be discussed, based on emerging evidence that PDAC stroma has a significant bearing on disease behaviour and response to therapy." (PMID 34680285, 2021).
tumor (continued). "This group has shown that PRMT5 is overexpressed in these tumours, compared to normal tissue, and that PRMT5 expression inversely correlated with survival." (PMID 33404912, 2021). "The combination of PRMT5 inhibition and ani-PD-L1 therapy resulted in an increase in the number and enhanced the function of tumor-infiltrating T cells." (PMID 35111150, 2021). "To date, little is known about how PRMT5 inhibitors affect immune cells in the tumor microenvironment or the human immune system." (PMID 35111150, 2021). "PRMT5 was also shown to associate with Programmed Cell Death Protein 4 (PDCD4) and reduce its tumour‐suppressor activity in MCF7 cells." (PMID 33462997, 2021). "In the present study, we report that PRMT5 facilitates the cell proliferation in vitro and tumor growth in vivo." (PMID 33664859, 2021). "More recently, Liu and colleagues reported that c-Myc directly interacts with PRMT5 and reduced expression of a variety of tumor suppressors." (PMID 33440687, 2021). "The higher PRMT5 expression was correlated with tumor size (P = 0.0457), tumor stage (P = 0.0172) and distant metastasis (P = 0.0381)." (PMID 33664859, 2021). "Both groups have independently reported that the combination of PRMT1 and PRMT5 inhibition has synergistic effects on tumour cell growth, at least partly mediated by methylthioadenosine phosphorylase (MTAP)." (PMID 33404912, 2021). "Since PRMT5 inhibitors not only have effects on tumor cells, but also affect the function of immune cells." (PMID 34522232, 2021). "The role of PRMT5 in tumor growth was observed by transplanted tumor models, and the function of T cells in tumor microenvironment and in vitro co-culture system was investigated through flow cytometry." (PMID 34522232, 2021). "PRMT5 inhibition not only decreased tumor cell survival but also increased the tumor cell expression of CD274 in vitro and in vivo, which activated the PD1/PD-L1 axis and eliminated CD8+T cell antitumor immunity." (PMID 35111150, 2021). "As we all know, T cells play an important role in antitumor immunity, we further investigated the effect of T cells on tumor growth in vivo and how PRMT5 affected the function of T cells in the tumor microenvironment." (PMID 34522232, 2021). "Further studies are needed define how systemic inhibition of PRMT5 will affect not only tumor cells, but various cell types found in the tumor microenvironment, including immune and other stromal cells." (PMID 32743345, 2020). "Compared to normal mucosa, ARG1, PRMT1, and PRMT5 were overexpressed in both tumor and tumor-adjacent tissue and DDAH2 solely in tumor-adjacent tissue." (PMID 32932854, 2020). "ROCK (RhoA-activated kinase) and MP (myosin phosphatase), respectively, phosphorylate and dephosphorylate PRMT5 threonine 80, to modulate PRMT5 activity, thereby pointing to a tumor suppressor role of MP in HCC." (PMID 32743345, 2020). "Increased expression of PRMT5 was found in lymphatic metastatic tissues compared to the corresponding primary tumor tissues." (PMID 33060569, 2020). "The cellular context, tissue dependence and genetic background that explain the oncogenic vs. tumor suppressor functions of PRMT5 require further studies." (PMID 32743345, 2020). "Most significantly, a coincidence was apparent between the expression of PRMT5 and E2F1 in human tumours, and elevated levels of PRMT5 and E2F1 correlated with poor prognosis disease." (PMID 32709847, 2020). "We further analyzed the correlation between PRMT5 and tumor progression by IHC on the second cohort of a 66-case tissue microarray." (PMID 33060569, 2020). "Upon analyzing the RNA-Seq data of CRC patients from the TCGA database using the GEPIA website, we found that PRMT5 is indeed overexpressed (q < 0.01) in CRC patient tumor samples when compared to normal colon and rectum tissue." (PMID 32731506, 2020).